TMEM9 (transmembrane protein 9)
Description:
Transmembrane protein that binds to and facilitates the assembly of lysosomal proton-transporting V-type ATPase (v-ATPase), resulting in enhanced lysosomal acidification and trafficking. By bringing the v-ATPase accessory protein ATP6AP2 and the v-ATPase subunit ATP6V0D1 together, allows v-ATPase complex formation and activation. TMEM9-controlled vesicular acidification induces hyperactivation of Wnt/beta-catenin signaling, involved in development, tissue homeostasis and tissue regeneration, through lysosomal degradation of adenomatous polyposis coli/APC. In the liver, involved in hepatic regeneration.
Synonyms: TMEM9A; DERM4
Tractability: Antibody: UniProt predicts a signal peptide or a membrane-spanning region. PROTAC: ubiquitination databases record sites on it; its protein half-life has been measured.
Gene: Protein-coding gene on chromosome 1 (201,134,772 to 201,172,330, reverse strand). Ensembl gene ENSG00000116857.
Subcellular location: Lysosome membrane; Late endosome membrane; Endosome, multivesicular body membrane
Subcellular location (Human Protein Atlas): Vesicles; Cytokinetic bridge; Microtubules; Mitotic spindle
Gene Ontology:
Molecular function: protein binding
Biological process: endosomal lumen acidification; lysosomal lumen acidification; positive regulation of canonical Wnt signaling pathway; proton-transporting V-type ATPase complex assembly; regulation of protein catabolic process
Cellular component: late endosome; late endosome membrane; lysosomal membrane; lysosome; multivesicular body membrane
Genetic constraint (gnomAD): Loss-of-function variants: 12 observed, 21.19 expected, observed/expected ratio (o/e) 0.57, 90% interval 0.36 to 0.92. The upper end of that interval is the gene's LOEUF score, 0.92, which puts it in group 3 of 6, group 1 being the genes least tolerant of losing a copy. Missense variants: 174 observed, 237.58 expected, observed/expected ratio (o/e) 0.73, 90% interval 0.65 to 0.83. Synonymous variants: 84 observed, 92.98 expected, observed/expected ratio (o/e) 0.9, 90% interval 0.76 to 1.08.
Homologues: Orthologues: chimpanzee TMEM9 (100% identical), macaque TMEM9 (100% identical), rat Tmem9 (98% identical), mouse Tmem9 (97% identical), guinea pig TMEM9 (97% identical), rabbit TMEM9 (96% identical), dog CACNA1S (96% identical), pig TMEM9 (93% identical), zebrafish tmem9 (70% identical), Caenorhabditis elegans R12C12.6 (34% identical), Drosophila melanogaster CG1161 (33% identical). Paralogues in human: TMEM9B (58% identical).
Diseases named in the same sentence as TMEM9 in open-access papers:
TMEM9 is named in the same sentence as 19 diseases in open-access papers, as found by Europe PMC text mining. Sharing a sentence is not in itself a finding about the gene and the disease. The quoted sentences say what the papers report.
breast carcinoma (3 papers, 2024 to 2025). "Many studies have demonstrated that TMEM9 is highly expressed in multiple human cancers, such as mammary tumors and hepatocellular and colorectal cancer." (PMID 38664392, 2024). "TMEM9 is frequently upregulated in various types of cancer, especially breast cancer." (PMID 38965614, 2024). "It has been reported that TMEM9 promotes the proliferation of breast cancer and HCC cells." (PMID 38664392, 2024).
colorectal cancer (3 papers, 2021 to 2024). A primary or metastatic malignant neoplasm that affects the colon or rectum. "Transmembrane protein 9 expression and Wnt/β-catenin signaling activation were associated with intracellular acidification induced colorectal cancer progression." (PMID 34681640, 2021). "In addition, several studies showed that TMEM9 could facilitate the assembly of v‐ATPase, which leads to vesicular acidification and lysosomal dysfunction that promotes tumor occurrence in hepatocellular carcinoma and colorectal cancer." (PMID 38664392, 2024). "TMEM9 promotes lysosome activation, and in turn facilitates the degradation of APC, which releases β-catenin and activates Wnt-signalling in liver cancer and colorectal cancer." (PMID 38965614, 2024).
hepatocellular carcinoma (3 papers, 2019 to 2024). A malignant tumor that arises from hepatocytes. "The current study elucidated the role of a long non‐coding RNA (lncRNA), FOXD2‐AS1, in the pathogenesis of hepatocellular carcinoma (HCC) and the regulatory mechanism underlying FOXD2‐AS1/miR‐150‐5p/transmembrane protein 9 (TMEM9) signalling in HCC." (PMID 31210410, 2019). "Treatment with BafA1 reduces tumor growth in TMEM9-expressing CRC and Hepatocellular carcinoma (HCC) xenografts, demonstrating the importance of lysosomes in tumor progression." (PMID 35632546, 2022).
liver cancer (2 papers, 2024 to 2025). An epithelial or non-epithelial malignant neoplasm that arises from the liver. "TMEM9 was found to be abnormally expressed in liver cancers, and it was described as an oncogene implicated in tumour development, invasion, and chemoresistance." (PMID 40535770, 2025).
lung adenocarcinoma (2 papers, 2024 to 2025). A carcinoma that arises from the lung and is characterized by the presence of malignant glandular epithelial cells. "In lung adenocarcinoma, TMEM9 activates the MEK/ERK/STAT3 pathway and induces vascular endothelial growth factor (VEGF) expression, a pathway also involved in psoriasis." (PMID 41153404, 2025). "Taken together, our data established TMEM9 as a candidate biomarker for the prognosis of lung adenocarcinoma and favored tumor progression." (PMID 38664392, 2024). "However, the prognostic potential and mechanistic role of TMEM9 in lung adenocarcinoma (LUAD) remain unclear." (PMID 38664392, 2024).
Alzheimer disease (1 paper, 2025). A progressive, neurodegenerative disease characterized by loss of function and death of nerve cells in several areas of the brain leading to loss of cognitive function such as memory and language. "Therefore, microglial Tmem9 may represent a promising therapeutic target for inhibiting synaptic loss in Alzheimer's disease." (PMID 39871402, 2025).
breast tumor (1 paper, 2024). "The lysosomal TMEM9-LAMTOR axis has been found to play an important role in controlling mTOR signaling integrity in breast tumor development." (PMID 38420434, 2024).
cognitive disorder (1 paper, 2025). A disease affects cognitive processes. "In an AD mouse model, it decreased the levels of microglial Tmem9 to inhibit the activation of complement, alleviated complement‐dependent synaptic loss, and eventually ameliorated emotional and cognitive disorders." (PMID 39871402, 2025).
Cognitive impairment (1 paper, 2025). Abnormal cognition is characterized by deficits in thinking, reasoning, or remembering. "Together, these results indicate that PE attenuated cognitive impairment in AD model mice, which could be abolished by overexpression of microglial Tmem9, and that knockdown of microglial Tmem9 mimicked the PE‐associated protection." (PMID 39871402, 2025). "Here, we show that physical exercise down‐regulated the microglial Tmem9 protein, inhibited C1q activation, and decreased C1q‐dependent microglial synapse engulfment, eventually ameliorating cognitive impairment in 5xFAD mice." (PMID 39871402, 2025).
tumor (6 papers, 2022 to 2025). "TMEM9 expression was also lower in in normal compared to tumor tissue, and lower expression of TMEM9 was associated with better prognosis when given AI therapy." (PMID 38965614, 2024). "Transmembrane protein 9, a member of family 3, has been reported to be overexpressed in several tumor types." (PMID 38255914, 2024). "We also provided a novel insight into a mechanism by which TMEM9 mediated tumor growth via MEK/ERK/STAT3/VEGF pathway in LUAD." (PMID 38664392, 2024). "Our observation that the tumor-promoting protein TMEM9 can regulate alternative autophagy provides new insight into the role of alternative autophagy in tumorigenesis." (PMID 39078420, 2024). "TMEM9 knockdown significantly reduced tumor volume and weight compared with the control group." (PMID 38664392, 2024). "The result showed that TMEM9 was highly expressed in the tumor tissues (P < 0.01)." (PMID 38664392, 2024). "In addition, downregulation of TMEM9 suppressed tumor growth and metastasis in vitro and in vivo models, and reduced HUVEC proliferation, migration, and tube formation in a cancer cell/HUVEC coculture model." (PMID 38664392, 2024). "The pan-cancer analysis demonstrated that TMEM9 was highly expressed in most tumor tissues." (PMID 38664392, 2024). "In addition, the molecular mechanisms of TMEM9-elicited tumor development remain unclear." (PMID 38664392, 2024). "In the study, we investigated the expression and function of TMEM9 in LUAD and demonstrated that TMEM9 promoted tumor cell proliferation, migration, and angiogenesis via increasing VEGF expression and secretion." (PMID 38664392, 2024). "We first observed a positive correlation between the expression level of TMEM9 and MVD in patient tumor tissues." (PMID 38664392, 2024). "Furthermore, when compared to control, recombinant VEGF (rVEGF) abolished the inhibitory effect of TMEM9-knockdown LUAD cells on HUVEC angiogenesis and tumor cell migration." (PMID 38664392, 2024).
cancer (4 papers, 2019 to 2024). A tumor composed of atypical neoplastic, often pleomorphic cells that invade other tissues. "To investigate the differences in TMEM9 expression between tumors and normal tissues, we analyzed the expression levels of TMEM9 in different tumors and their corresponding normal tissues of pan‐cancer using transcriptomic data from TCGA and GTEx databases." (PMID 38664392, 2024). "YIPF6, TMEM9, and PSME3 have been associated with cancer and SPIRE1 reportedly contributes to metastatic potential." (PMID 30913233, 2019).
infection (1 paper, 2011). The state of being infected such as from the introduction of a foreign agent such as serum, vaccine, antigenic substance or organism. "Its ectopic expression in Vero cells, that we achieved either by transfection or by lentiviral transduction, did not render the cells susceptible to infection by the IAPE Env pseudotypes (not shown), definitively demonstrating that TMEM9 is not a receptor for the IAPE Env." (PMID 22028653, 2011).
TMEM9 also shares sentences with these, for which no sentence is quoted: Anxiety (1 paper); cognitive decline (1); colon cancer (1); lung carcinoma (1); psoriasis (1); triple-negative breast carcinoma (1); viral infections (1).